IL1B (interleukin 1 beta)
Diseases named in the same sentence as IL1B in open-access papers (continued):
Sharing a sentence is not in itself a finding about the gene and the disease.
endometritis (77 papers, 2009 to 2025). An acute or chronic, usually bacterial infectious process affecting the endometrium. "Their research also highlighted the role of the ECS components in modulating inflammatory responses, with elevated levels of pro-inflammatory cytokines such as TNF and IL1B associated with endometritis." (PMID 39273135, 2024). "Among these inflammatory cytokines, IL-1β is critical to the host’s defensive response to infection and injury and is associated with endometritis." (PMID 37570258, 2023). "Meanwhile, endometritis caused by bacterial infection usually involves inflammatory factors such as IL-1β, IL-6, and TNF-α." (PMID 36846263, 2023). "Uterine infections increase expression of mRNA transcripts in the endometrium that encode molecules associated with inflammation, such as the cytokines IL-1β and IL-6, and the chemokine IL-8." (PMID 24209779, 2013). "Previous studies by Fumuso and co-workers showed that mares susceptible to persistent endometritis had significant upregulated cellular immune response (IL-1β, IL-6, TNF-α and IL-8) and down-regulated anti-inflammatory activity (IL-10) compared to resistant mares at estrous baseline levels." (PMID 22458733, 2012). "In summary, the present study provided strong evidence of the protective effects of TREM‐1 deficiency against LPS‐induced endometritis in mice, the mechanism of which could be deduced as knocking out of the Trem‐1 inhibited the LPS‐induced production of IL‐1β, IL‐6 and TNF‐α." (PMID 31365951, 2019). "The previous study showed that in the patients with endometritis, the cyclic GMP–AMP synthase(cGAS)-STING pathway was activated and the expression of cytokine-encoding genes, including IL-1β, IL-8, IL-6 and IFN-β1 were increased." (PMID 39992946, 2025). "Numerous inflammatory mediators, including tumor necrosis factor α (TNF-α), and interleukin (IL)-1β, IL-6, and IL-8, are released during endometritis, and inhibition of these inflammatory factors can effectively reduce the severity of bacterial endometritis." (PMID 40431224, 2025). "The ABX+DI+Guanosine+E. coli group reduced endometritis inflammatory markers, including IL‐1β and TNF‐α concentrations and expression level, compared with the ABX+DI+E. coli group." (PMID 40227949, 2025). "Berberine and carvacrol, respectively, were found to significantly reduce the expression of TNF-a, IL-1β, IL-6, and IL-8 after treatment of endometritis in mice, and the differences were significant compared with those in the model group (p < 0.01)." (PMID 40431224, 2025). "LPS challenge triggered a robust upregulation of il1b, tnfa, and il6 in WT mice, confirming the successful induction of endometritis." (PMID 41583494, 2025). "One study using Biochemical Decoction to treat LPS-induced endometritis found that IL-1β, IL-6, and IL-8 levels were significantly reduced in the treatment group compared to the LPS group." (PMID 41002185, 2025). "The results showed that the TCMF significantly alleviated the symptoms of endometritis, reduced epithelial sloughing in the uterus, and significantly lowered the mRNA levels of IL-1β and IL-6 in uterine tissue." (PMID 41002185, 2025). "Increased inflammatory cytokines TNF-α, IL-6, and IL-1β were observed in patients with endometritis." (PMID 38169293, 2024). "The results showed that S. aureus significantly increased the levels of MPO, TNF‐α, IL‐1β and IL‐6 in uterine tissue, and increased the expression of p‐p65 and p‐IκBα proteins in uterine tissue to induce endometritis in mice (p < 0.05)." (PMID 39042561, 2024). "In this study, LPS-induced BEND cell inflammation was used to establish a model of endometritis effects of LPS on expression levels of inflammatory factors in BEND cells IL-1β, IL-6, IL-8, TNF-α for further analysis." (PMID 39682333, 2024). "Numerous studies have demonstrated that LPS stimulates the production of IL-6, IL-1β, and TNF-α, which are also implicated in the pathogenesis of endometritis." (PMID 37570258, 2023).
endometritis (continued). "In LPS-induced endometritis in mice, alpinetin exerts its anti-inflammatory effects by inhibiting the expression of IL-6, IL-1β, and TNF-α." (PMID 37570258, 2023). "For instance, IL1β is significantly upregulated in PBIE in susceptible mares, while IL6 or TNFα are predominant in chronic subclinical endometritis and overexpression of IL1β, IL6, and TNFα is observed in subacute suppurative endometritis." (PMID 37869492, 2023). "Three examined cytokines, including IL-1, IL-1β, and IL-6, were found to have increased gene expression in buffaloes with endometritis compared to healthy animals." (PMID 37368756, 2023). "NLRP3, responsible for the maturation and secretion of IL-1β, has been proven to be related to the development of endometritis in dairy cows." (PMID 37570258, 2023). "First, we tested the effects of heat-killed C. butyricum and spent culture supernatants (SCS) from C. butyricum on TNF-α and IL-1β expression in E. coli-induced endometritis." (PMID 36321897, 2022). "Meanwhile, previous studies have shown that TNF-α, IL-6, and IL-1β were upregulated in S. aureus-induced endometritis." (PMID 35937303, 2022). "In this study, we successfully established an endometritis model in mouse using Escherichia coli; endometrial integrity was destroyed, inflammatory cells infiltrated and the expression of IL-6, IL-1β, TNF-α was significantly up-regulated." (PMID 35744807, 2022). "Consistent with results from previous studies, TNF-α and IL-1β concentrations were markedly elevated in the E. coli-induced endometritis group in this study." (PMID 36321897, 2022). "Matrine reduced the expression of TNF-α and IL-1β and attenuated the uterus injury in the lipoteichoic acid-induced mouse endometritis model." (PMID 36249421, 2022). "Mice were injected with different concentrations of Escherichia coli (E. coli) for 24 h to establish a model of endometritis, and we detected the mRNA and protein expressions of IL-6, IL-1β and TNF-α in the mouse uterine tissues." (PMID 35744807, 2022). "IFNτ acts as an anti-inflammatory agent by suppressing the NFkβ mechanism and inhibits production of IL1B and TNFα in the endometritis in mice." (PMID 36428366, 2022). "qRT-PCR results showed that the endometritis tissues secreted the proinflammatory cytokines IL-1β, IL-6, and TNF-α, but there was a decreased secretion of IL-10, an anti-inflammatory mediator." (PMID 34504639, 2021). "We found that the IL-1β and IL-6 levels were significantly elevated in uterine tissues with endometritis." (PMID 35003515, 2021). "Some key inflammatory mediators have been found to be related to the occurrence and development of endometritis, including IL-1β and IL-6.Thus, the expression levels of IL-1β and IL-6 were measured." (PMID 35003515, 2021). "In contrast, elevated serum and tissue concentrations of pro-inflammatory cytokines, including TNF-α, IL-1β, and IL-6, were observed in cows with metritis, endometritis, or subclinical endometritis." (PMID 33132596, 2020). "Conversely, upstream regulators including TNF, LPS, interferon, IL‐1β, and IL‐6 were activated in oocytes of bacteria‐infused heifers at Day 60 long after the resolution of uterine infection." (PMID 32821881, 2020). "Second, we focused on the protective effects of AS IV against LPS-induced endometritis concerning the aspects of histopathological changes, inflammatory cytokine levels (IL-1β and TNF-α), concentration of NO, and myeloperoxidase activity in the uterus." (PMID 30669661, 2019). "Earlier work has identified upregulated expression of the potent inflammatory cytokine IL-1β early post-partum, in cows which subsequently develop endometritis." (PMID 30804935, 2019). "Earlier work has identified elevated gene expression of IL1B in endometrial biopsies obtained from cows diagnosed with post-partum endometritis, but our study is the first to confirm elevated levels of IL-1β protein in endometrial samples." (PMID 30804935, 2019).
endometritis (continued). "Seven DPP, endometrial IL-1β protein levels were significantly higher in animals that proceeded to develop endometritis at 21 DPP." (PMID 30804935, 2019). "IL-1β protein levels were quantified by ELISA and found to be significantly elevated in animals diagnosed with cytological endometritis and PVD at both time points." (PMID 30804935, 2019). "We identified IL-1β levels in CVM at 7 days postpartum to be a predictor of cows likely to subsequently develop endometritis 3 weeks after calving." (PMID 30117040, 2018). "In our previous study, we found that IL-1β is highly elevated in cows with clinical endometritis early postpartum." (PMID 30117040, 2018). "This is in agreement with results of molecular studies performed on the endometria of cows, in which mRNAs for both IL-1β and IL-6 were over-expressed during the course of endometritis." (PMID 27152525, 2016). "Cows with subclinical endometritis had higher leptin and IL-6 concentrations compared to normal cows (P < 0.05), whereas IL-1β concentrations were higher in cows with any diagnosed uterine inflammatory conditions compared to normal cows (P < 0.05)." (PMID 24209779, 2013). "It is possible that TNF-α, IL-1β, IL-4 and IL-10 significantly generated during endometritis, by increasing the viability of stromal cells, may affect the regeneration of endometrial cells damaged by inflammation." (PMID 39843578, 2025). "However, pretreatment of luteolin significantly attenuated TNF-α, IL-6, and IL-1β production in S. aureus–induced endometritis mice." (PMID 38169293, 2024). "Furthermore, leonurine effectively reduces levels of inflammatory cytokines, such as tumor necrosis factor-alpha (TNF-α), interleukin (IL)-6, and IL-1β (p < 0.01), which play a crucial role in regulating acute endometritis." (PMID 39062636, 2024). "The contents of TNF‐α and IL‐1β were detected by ELISA in S. aureus‐induced endometritis model." (PMID 39462269, 2024). "We speculate that caspase 4 may be activated by NETs during endometritis and cleave pro-IL-1β, pro-IL-18, and GSDMD to induce pyroptosis." (PMID 36430491, 2022). "Pro-inflammatory cytokines such as TNF-α and IL-1β have been found in endometritis." (PMID 36321897, 2022). "TNF-α and IL-1β content increases in inflamed tissues, including endometritis." (PMID 36230459, 2022). "In addition, oridonin can also resist a series of inflammatory reactions including LPS-induced inflammation in human gingival fibroblasts, IL-1β-induced inflammation in human osteoarthritis chondrocytes and LPS-induced endometritis." (PMID 34295243, 2021). "In addition, cows with metritis or clinical endometritis show higher serum concentrations of leptin, adiponectin, IL-1β, IL-6and TNF-α." (PMID 31311492, 2019). "Additionally, IL-1β levels were also recently shown to be significantly higher in cervical-vaginal mucus samples from cows with endometritis when compared to healthy cows 7 and 21 DPP." (PMID 30804935, 2019). "Hence, inhibition of NLRP3-caspase-1-mediated IL-1β production may be a possible target for ameliorating endometritis." (PMID 37570258, 2023). "This study investigates postpartum bovine uterine tissues, comparing inflammatory cytokines (IL-1β, IL-6, TNF-α) and oxidative-stress-related factors (GPx, SOD, CAT) between healthy and endometritis groups." (PMID 40646747, 2025). "Endometritis is characterized by the high expression of CD14, TLR4, IL-1α, IL1-β, IL-6, IL-8, and TNF-α in uterine tissue and cervical mucus." (PMID 39858163, 2025). "Studies have found that Escherichia coli increases inflammatory factors, such as iNOS, IL-1β, TNF-α, IL-6, etc., through the NF-κB signaling pathway, leading to endometritis." (PMID 40514455, 2025). "On the other hand, it was reported that the peroxisome proliferator-activated receptor γ (PPARγ) inhibits pro-inflammatory cytokines (TNFα, IL-1β, and IL-6), TLR4, and NF-κB, relieving LPS-induced endometritis in pig endometrial epithelial cells (EECs)." (PMID 39408650, 2024).
endometritis (continued). "The research in this study demonstrated that the transvaginal instillation of a specific amount of LPS induced acute endometritis in mice, leading to increased levels of pro-inflammatory cytokines such as TNF-α, IL-6, and IL-1β." (PMID 39062636, 2024). "✧Prevented the endometritis via inhibition of MPO, NF-Κb, TNF-α, and IL-1β.✧Enhanced the expressions of Nrf2 and HO-1 levels and suppressed the MDA content." (PMID 39408650, 2024). "The results showed that the IL-6, IL-1β, and TNF-α were decreased, and the IL-10 was increased in mice with endometritis treated with naringin." (PMID 39234103, 2024). "And the signaling transduction of PGD2 through the DP1 receptor in bacteria-mediated endometritis in dairy cows was found to suppress activation of NF-κB and P38 MAPK signaling, thus reducing expression of IL-6, IL-1β, and TNF-α." (PMID 37891648, 2023). "The results showed that C. butyricum decreased E. coli-induced endometritis by downregulating the proinflammatory cytokines TNF-α and IL-1β to directly inhibit the inflammatory response." (PMID 36321897, 2022). "First, we demonstrated that PGD2 inhibited the secretion of the inflammatory cytokines IL-1β, IL-6, and TNF-α to some extent, contributing to inhibition of the phosphorylation of p38, ERK, and NF-κB in bovine endometritis." (PMID 36435808, 2022). "The results of this study highlight the important role of IL1B and IL1RA during endometritis and the potential of the IL1RA/IL1B ratio as a possible biomarker for SE." (PMID 36496884, 2022). "For instance, one study finds that miR‐34a induces the release of the proinflammatory cytokines including IL‐1β, IL‐6, and TNF‐α in endometritis." (PMID 34861059, 2022). "Several studies have found that the mRNAs of interleukin (IL) 1A, IL1B, IL6, IL8, chemokine CXL ligand (CXCL) 3, and CXCL5 are up-regulated in dairy cows with endometritis." (PMID 33718475, 2021). "In this experiment, bAD-MSCs were co-cultured within a bovine endometrial epithelial cell inflammation model; we found that the levels of IL-1β, TNF-α, and IL-6 were significantly lower than those in the endometritis model group." (PMID 34746277, 2021). "The results showed that LPS treatment for 12 h significantly increased the levels of IL-6, IL-1β, and TNF‐α, indicating the successful establishment of the LPS-induced endometritis model in mice." (PMID 34976866, 2021). "The results of qPCR assay showed that the secretion of pro‐inflammatory cytokines IL‐1β and TNF‐α was markedly increased in the uterine tissues from mice with endometritis." (PMID 31756048, 2020). "The expression of the pro-inflammatory mediators IL-1β and TNF-α were detected using a qPCR assay of the LPS-induced endometritis treatment." (PMID 28223539, 2017). "In this study, postpartum dairy cows diagnosed with metritis, clinical endometritis, or subclinical endometritis had higher serum concentrations of adiponectin, TNF-α, IL-1β and IL-6 compared to normal cows." (PMID 24209779, 2013). "Real-time RT-PCR has revealed that CXCL5, IL1B, IL8 and TNF mRNA are significantly higher expressed in the endometrium of cows with subclinical or clinical endometritis than in healthy cows." (PMID 21176181, 2010). "In vivo, it alleviated LPS-induced endometritis in mice and reduced TNF-α and IL-1β levels." (PMID 40430456, 2025). "The results showed that the mRNA levels of IL-1β, IL-6, IL-8, and IL-18 were significantly reduced in the drug treatment groups compared to the LPS group, which is consistent with results from other studies using TCMF treatments for endometritis." (PMID 41002185, 2025). "The RT-qPCR analysis of the inflammatory cytokines (IL-1β, IL-6, TNF-α) in the two groups demonstrated that the mRNA expression levels of IL-1β, IL-6, and TNF-α were significantly upregulated in the endometritis group compared to the healthy group (* p < 0.05; ** p < 0.01)." (PMID 40646747, 2025).
endometritis (continued). "Moreover, a study revealed that interferon-tau (IFN-τ) prevents S. aureus-induced endometritis by downregulating the expressions of NF-κB, matrix metalloproteinase 9 (MMP 9), TLR2, TNF-α, IL-1β, and IL-6 levels." (PMID 39408650, 2024). "In addition, our study also verified the effects of inflammatory cytokines (IL-1β, IL-6, and TNF-α) in the endometritis model." (PMID 36846263, 2023). "Pretreatment with heat-killed C. butyricum did not alter TNF-α and IL-1β levels in E. coli-induced endometritis." (PMID 36321897, 2022). "We also found that IAld, indole, and IPA treatment alleviated E. coli-induced endometritis, which was shown by improved uterine inflammatory injury and reduced inflammatory markers including MPO activity, TNF-α, and IL-1β compared with the E. coli group." (PMID 35727038, 2022). "Previous studies show that mRNA of proinflammatory cytokines interleukin-1 alpha (IL1A), IL1B, IL6, and TNF and expression of chemokines IL8 and CXCL5 increased in endometrial epithelial cells during the estrous cycle and subclinical or clinical endometritis." (PMID 33324700, 2020). "In the present study, AS IV inhibited LPS-induced production of IL-1β and TNF-α, meaning that AS IV could attenuate LPS-induced endometritis by inhibiting these inflammatory cytokines." (PMID 30669661, 2019). "It has been reported that suppressing the expression of IL-1β and TNF-α could attenuate LPS-induced endometritis." (PMID 30669661, 2019). "Our results revealed that activation of NF-κB in LPS-induced BEND cells in vitro and endometritis in vivo promoted the transcription of miR-223 and thus inhibited the activation of inflammatory mediators of NLRP3-mediated IL-1β production to protect the uterus from inflammatory damage." (PMID 30186287, 2018). "They suggested that IL-1β, IL-8, and TNF-α might represent potential marker genes for the detection of cows with subclinical endometritis and for monitoring new therapeutic approaches." (PMID 27051191, 2016). "The results of the current investigation demonstrated that PRP is capable of effectively decrease gene expression of pro-inflammatory factors IL-1β, I-L8, COX2 and iNOS after stimulation by LPS, prospecting its possible use in regenerative therapy in in vivo endometritis." (PMID 27619959, 2016). "Recently, it was suggested that CXCL5, IL1B, IL8 and TNF may be suitable markers for the detection of subclinical endometritis because mRNA levels were elevated compared with samples from healthy cows." (PMID 21176181, 2010). "Since IL-1β and IL-18 are the final cytokines in the pyroptosis pathway, the significant inhibition of LPS-induced IL-1β and IL-18 mRNA levels by TCMF suggests that their anti-endometritis mechanisms may be related to pyroptosis, which warrants further investigation." (PMID 41002185, 2025). "Hence, we concluded that ICA might express its protective effect by attenuation of the production of IL-1β, IL-6, and TNF-α as well as boosting the production of IL-10 in LPS-induced endometritis." (PMID 36142129, 2022). "In the present study, the overexpression of ISG15 significantly reduced the mRNA expression levels of IL-1β, IL-6 and IL-8 in gEECs following LPS treatment, while the silencing of ISG15 had the opposite effect, indicating that ISG15 plays a protective role in goat endometritis." (PMID 34573559, 2021). "An increase in the relative mRNA abundance of pro-inflammatory cytokines (IL-1β, IL-8, IL-6, and TNF-α) has also been detected in the cervical mucus of buffalo along with low intra-follicular estradiol levels, which suggests that endometritis could impede the follicular steroidogenesis." (PMID 39858163, 2025). "Notably, the LPS-induced tissue levels of IL-1β, IL6, and TNF-α significantly decreased with Cl-amidine treatment, indicating that inhibition of NETs formation in the process of endometritis could be advantageous in protecting uterine tissue from damage and ultimately altered endometritis." (PMID 35565576, 2022).